STK17B (serine/threonine kinase 17b)
Description:
Phosphorylates myosin light chains (By similarity). Acts as a positive regulator of apoptosis.
Synonyms: DRAK2
Tractability: Small molecule: a structure with a bound ligand is known; a high-quality ligand is known; it has a high-quality binding pocket; it belongs to a druggable protein family. Antibody: UniProt places it where antibodies can reach, with medium confidence; its Gene Ontology location is reachable by antibodies, with medium confidence. PROTAC: it is named in the literature on targeted protein degradation; ubiquitination databases record sites on it; its protein half-life has been measured; a small molecule that binds it is known.
Target class: CAMK protein kinase group; Kinase; CAMK protein kinase DAPK family; Protein Kinase; Enzyme
Chemical probes: SGC-STK17B-1 (high quality)
Gene: Protein-coding gene on chromosome 2 (196,133,583 to 196,176,503, reverse strand). Ensembl gene ENSG00000081320.
Subcellular location: Nucleus; Cell membrane; Endoplasmic reticulum-Golgi intermediate compartment
Subcellular location (Human Protein Atlas): Nucleoplasm
Gene Ontology:
Molecular function: ATP binding; protein serine/threonine kinase activity; protein kinase activity; protein serine kinase activity
Biological process: intracellular signal transduction; positive regulation of fibroblast apoptotic process; protein phosphorylation; positive regulation of apoptotic process; protein autophosphorylation; apoptotic process; programmed cell death
Cellular component: nucleoplasm; nucleus; actin cytoskeleton; endoplasmic reticulum-Golgi intermediate compartment; plasma membrane
Genetic constraint (gnomAD): Loss-of-function variants: 17 observed, 28.67 expected, observed/expected ratio (o/e) 0.59, 90% interval 0.41 to 0.89. The upper end of that interval is the gene's LOEUF score, 0.89, which puts it in group 3 of 6, group 1 being the genes least tolerant of losing a copy. Missense variants: 308 observed, 377.63 expected, observed/expected ratio (o/e) 0.82, 90% interval 0.74 to 0.9. Synonymous variants: 130 observed, 122.84 expected, observed/expected ratio (o/e) 1.06, 90% interval 0.92 to 1.22.
Homologues: Orthologues: chimpanzee STK17B (99% identical), macaque STK17B (97% identical), dog STK17B (96% identical), rabbit STK17B (96% identical), pig STK17B (95% identical), guinea pig STK17B (92% identical), rat Stk17b (92% identical), mouse Stk17b (91% identical), zebrafish stk17b (53% identical), Drosophila melanogaster Drak (35% identical). Paralogues in human: STK17A (54% identical).
Diseases named in the same sentence as STK17B in open-access papers:
STK17B is named in the same sentence as 47 diseases in open-access papers, as found by Europe PMC text mining. Sharing a sentence is not in itself a finding about the gene and the disease. The quoted sentences say what the papers report.
hepatocellular carcinoma (6 papers, 2018 to 2025). A malignant tumor that arises from hepatocytes. "While no direct evidence yet connects STK17B to heart disease, numerous studies associate dysregulated STK17B expression with poor clinicopathological features in hepatocellular carcinoma." (PMID 40124544, 2025). "As a member of the death-associated protein kinase family of serine/threonine kinases, the STK17B has been associated with diverse diseases such as hepatocellular carcinoma." (PMID 35620482, 2022). "As a member of the death-associated protein kinase (DAPK) family, STK17B plays an important role in the regulation of cellular apoptosis and has been considered as a promising drug target for hepatocellular carcinoma." (PMID 35889528, 2022). "STK17B, which has high expression in lymphoid tissue, has been indicated associated with hepatocellular carcinoma and some other cancers by previous studies." (PMID 35171924, 2022). "It has been well-established that overexpression of STK17B has closely associated with the tumorigenesis of hepatocellular carcinoma (HCC) and breast cancer, and inhibition of STK17B inhibited HCC tumorigenesis and metastasis via AKT/GSK3β/Snail signaling." (PMID 35889528, 2022). "Overexpression of STK17B plays a crucial role in hepatocellular carcinoma and thus, inhibition of STK17B catalytic activity in cells implies clinical utility in the treatment of this malignancy." (PMID 35620482, 2022). "MiR-455 inhibits the EMT process in pancreatic cancer and hepatocellular carcinoma by modulating the Wnt/β-catenin and STK17B/AKT/GSK-3β/Snail signaling, respectively." (PMID 34174908, 2021). "STK17B is upregulated in hepatocellular carcinoma tissues and cell lines." (PMID 35171924, 2022). "On the contrast, STK17B is highly expressed in hepatocellular carcinoma (HCC) tissues, which was considered predicting a poor prognosis." (PMID 35171924, 2022).
breast carcinoma (5 papers, 2018 to 2022). "Besides, the breast cancer cell line with depletion of STK17B retarded tumorigenesis and inhibited tumor growth in a xenograft model." (PMID 35171924, 2022). "Additionally, STK17B was over-expressed in basal-like and HER2-enriched breast cancer, and silence of STK17B retarded tumorigenesis and tumor growth in xenograft model." (PMID 35171924, 2022).
chronic lymphocytic leukemia (5 papers, 2020 to 2024). "STK17B has been suggested as a potential prognostic marker in chronic lymphocytic leukemia, multiple myeloma, and skin cutaneous melanoma." (PMID 39502695, 2024). "MIR155HG is correlated with high grade glioma, leukemia, and chronic lymphocytic, and STK17B is related to colon squamous cell carcinoma." (PMID 34370778, 2021). "Previous studies have demonstrated that STK17B could be an independent prognostic factor in chronic lymphocytic leukemia." (PMID 35171924, 2022).
autoimmune disease (4 papers, 2015 to 2022). A disorder resulting from loss of function or tissue destruction of an organ or multiple organs, arising from humoral or cellular immune responses of the individual to their own tissue constituents. "It has been found that STK17B affected autoimmune diseases via regulating T cell survival." (PMID 35171924, 2022).
diabetes (3 papers, 2020 to 2025). "The chemical inhibition of STK17B has been proposed as a potential diabetes treatment." (PMID 33302351, 2020). "STK17B has been proposed as a novel target in the treatment of diabetes." (PMID 33302351, 2020).
melanoma (3 papers, 2022 to 2025). A malignant, usually aggressive tumor composed of atypical, neoplastic melanocytes. "The enrichment results of our study revealed that differential expression of STK17B in melanoma patients was related to S. aureus infection." (PMID 35171924, 2022). "A further subgroup analysis showed that low STK17B was correlated with worse OS in N and M Stage, pathologic stage, radiation therapy, gender, race, melanoma ulceration, age, melanoma Clark level, Breslow depth, tumor site, BRAF status of SKCM patients." (PMID 35171924, 2022). "Our study also demonstrated the correlation between STK17B expression and immune-related progress in melanoma patients." (PMID 35171924, 2022). "Besides, there is few literature about the relationship of STK17B and melanoma." (PMID 35171924, 2022). "This this end, human donor-derived T cells were co-cultured with melanoma cells and stimulated with a melanoma targeting T cell bispecific antibody (MCSP-TCB) in presence of STK17A- or STK17B-selective compounds." (PMID 39502695, 2024). "Low STK17B was similarly correlated with worse DSS in T and M Stage, pathologic stage, melanoma Clark level, Breslow depth, melanoma ulceration, tumor site, BRAF status, age, race, gender, radiation therapy of SKCM patients." (PMID 35171924, 2022). "Notably, STAT1 was involved exclusively in Stage 4–specific synergistic relationships within the melanoma network, whereas TNFSF14, STK17B, SAMD3, PLAC8, and LYN were all Stage 1–specific synergistic genes that synergized with FENDRR." (PMID 40728857, 2025). "There were significant differences in subgroups of TNM stage, melanoma ulceration, pathologic stage, radiation therapy, gender, age, Breslow depth, BRAF status, indicating that STK17B expression level could impact the prognosis in SKCM patient with different pathological stages." (PMID 35171924, 2022). "Besides, STK17B expression was significantly related to some clinicopathological characteristics in SKCM patients including T stage, Breslow depth, radiation therapy, melanoma Clark level, and pathologic stage." (PMID 35171924, 2022).
acute myeloid leukemia (2 papers, 2021 to 2022). Acute myeloid leukemia (AML) is a group of neoplasms arising from precursor cells committed to the myeloid cell-line differentiation. "MYB is known to suppress apoptosis in acute myeloid leukemia cells by transcriptional repression of DRAK2 alias STK17B." (PMID 34294125, 2021).
insulinoma (2 papers, 2020 to 2025). "The downregulation of STK17B was able to prevent the inflammatory-induced cell death of insulinoma cells." (PMID 33302351, 2020).
leukemia (2 papers, 2018 to 2021). A malignant (clonal) hematologic disorder, involving hematopoietic stem cells and characterized by the presence of primitive or atypical myeloid or lymphoid cells in the bone marrow and the blood. "However, a consensus of STK17B’s function in cancer was not reached in previous studies, because STK17B may act as a tumor suppressor in leukemia and colorectal cancer." (PMID 29445189, 2018).
skin cutaneous melanoma (2 papers, 2022 to 2024). "The correlation between the STK17B expression and clinicopathological characteristics of skin cutaneous melanoma patients." (PMID 35171924, 2022).
liver cancer (1 paper, 2024). An epithelial or non-epithelial malignant neoplasm that arises from the liver. "Overexpression of STK17B is known to promote the proliferation and metastasis of liver cancer cells." (PMID 38978021, 2024). "In the ceRNA network of liver cancer, STK17B interacts with the LINC00426 lncRNA via 5 different miRNAs." (PMID 38978021, 2024).
non-Hodgkin lymphoma (1 paper, 2022). Distinct from Hodgkin lymphoma both morphologically and biologically, non-Hodgkin lymphoma (NHL) is characterized by the absence of Reed-Sternberg cells, can occur at any age, and usually presents as a localized or generalized lymphadenopathy associated with fever and weight loss. "Similarly, the significant correlations can also be found between the abnormal expression of STK17B and clinicopathologic variables in non-Hodgkin’s lymphoma." (PMID 35171924, 2022).
Sepsis (1 paper, 2025). Sepsis is defined as life-threatening organ dysfunction caused by a dysregulated host response to infection. "STK17B was also identified as a significant hub gene involved in the pathogenesis of sepsis, aligning with our results." (PMID 40124544, 2025).
spinocerebellar ataxias (1 paper, 2021). "Furthermore, STK17B was identified as a molecule being dysregulated in three more mouse models of diverse types of spinocerebellar ataxias (SCAs)." (PMID 34536317, 2021).
thyroid (1 paper, 2013). "We subsequently observed a consistent result in a series of thyroid cancer cell lines from different human tumors; high STK17B expression was observed in the most undifferentiated human anaplastic thyroid cells (8505c, Hth7 and Hth83), which are characterized by very low or null PAX8 levels." (PMID 24086368, 2013).
thyroid cancer (1 paper, 2013). "In addition to identifying a potential role of TSHR variants in cPTC risk, we have detected and independently replicated for the first time an epistatic relationship between the PAX8 and STK17B genes in thyroid cancer susceptibility." (PMID 24086368, 2013). "We identified and replicated an interaction between variants in PAX8 and STK17B, suggesting they may be new players in thyroid cancer susceptibility." (PMID 24086368, 2013). "Furthermore, we demonstrated an inverse correlation between expression of PAX8 and STK17B in a set of cell lines derived from human thyroid carcinomas." (PMID 24086368, 2013).
tumor (11 papers, 2009 to 2024). "The underlying mechanism might be high STK17B expression leading to high infiltration level of immune cells which contribute to resist tumor cells." (PMID 35171924, 2022). "Moreover, clinicopathological analysis revealed that STK17B expression level was positively associated with tumor size (P = 0.044), TNM stage (P = 0.004), and venous invasion (P = 0.031), indicating poor clinicopathological feature." (PMID 29445189, 2018). "Finally, our results for individual variants in TSHR and possibly TG, and the epistatic effect of the SNPs in PAX8 and STK17B, all apparently stronger for specific disease subtypes, stress the potential importance of tumor characterisation and stratification in association studies." (PMID 24086368, 2013). "Next, we demonstrated that pharmacologic inhibition of STK17B translates into enhanced antitumor efficacy in combination with a checkpoint inhibitor in a highly immunogenic syngeneic tumor model (MCA205)." (PMID 39502695, 2024). "STK17B was also identified in an in vivo CRISPR screen in tumor-bearing animals to identify novel cancer immunotherapy targets, where STK17B-depleted T cells were highly enriched in the tumor-infiltrating lymphocyte population." (PMID 39502695, 2024). "Studies have also shown that STK17B is highly expressed in certain malignancies and is involved in tumor proliferation and metastasis." (PMID 39502695, 2024). "We obtained evidence that STK17B was upregulated in HCC tissues, and we determined that the upregulation was associated with tumor size, TNM stage, and venous invasion by analyzing the clinicopathological features." (PMID 29445189, 2018). "Previously, several studies have reported that STK17B was involved in tumor progression, and there was also a study demonstrated its upregulation in HCC." (PMID 29445189, 2018). "However, in vivo assessment of the highly potent and selective STK17B inhibitor BLU7482 found inconsistent antitumor activities across two mouse syngeneic tumor models." (PMID 39502695, 2024). "Future research could also utilize slower growing tumor models to allow sufficient time for the immune system to mount an antitumor immune response in the presence of STK17B inhibitors, alone or in combination with immune checkpoint inhibitors." (PMID 39502695, 2024). "Above results suggested that STK17B was an important factor influencing clinicopathological characteristics and could be a possible tumor biomarker and drug target." (PMID 35171924, 2022). "EMT has a critical role in tumor metastasis, therefore, we sought to ascertain whether a relationship exists between STK17B and EMT." (PMID 29445189, 2018). "Thus, the information indicated that STK17B may have dual functions in tumor progression, and we suspected that STK17B functions in a disease-dependent or cellular-dependent manner." (PMID 29445189, 2018). "It has been identified that high expression level of STK17B in HCC was strikingly related to poor clinicopathological feature, including tumor size, TNM stage, and venous invasion." (PMID 35171924, 2022). "Clinicopathological analysis revealed that STK17B was related to TNM stage and venous invasion, which implied a potential function of STK17B in tumor migration and invasion." (PMID 29445189, 2018).
cancer (10 papers, 2009 to 2024). A tumor composed of atypical neoplastic, often pleomorphic cells that invade other tissues. "Pdgfrl is a platelet-derived growth factor receptor-like gene that has been implicated in certain cancers in humans and Stk17b, serine/threonine kinase, has been associated with signal transduction and apoptosis." (PMID 38419006, 2024). "The association between STK17B expression in various types of cancers was analyzed." (PMID 35171924, 2022). "This work investigated the serine/threonine protein kinase STK17B as a potential cancer immunotherapy target." (PMID 39502695, 2024). "While STK17B has been de-prioritized as a cancer immunotherapy target based on the findings reported here, the methodology and assays validated in this research can be applied to future studies." (PMID 39502695, 2024). "This allowed us to evaluate the potential of STK17B inhibition as an approach for cancer immunotherapy." (PMID 39502695, 2024). "We explored the expression differences of STK17B in 33 human cancers and corresponding normal tissues based on the TCGA and UCSC data sets." (PMID 35171924, 2022). "STK17B, also known as DRAK2, has also been connected to T cell function and to proliferation in cancer." (PMID 30800143, 2019). "Some researches revealed that STK17B was deregulated in some cancers and have important role in cancer progression." (PMID 29445189, 2018). "Consequently, STK17B represents an attractive potential target for cancer immunotherapy." (PMID 39502695, 2024). "Serine/threonine kinase 17B (STK17B), also known as DAP kinase-related apoptosis-inducing protein kinase 2 (DRAK2), is a member of the DAPK family which has emerged as a potential cancer immunotherapy target." (PMID 39502695, 2024). "Analyses of this research revealed that expression of STK17B was in obvious connection with OS and DSS for SKCM so that it could be regarded as a new prognostic biomarker of this cancer for further clinical study." (PMID 35171924, 2022). "The focus of this study was to understand the function of STK17B in T cells, as studies on T cells from STK17B knockout mice have demonstrated a lower threshold for TCR stimulation and that they can respond to suboptimal antigens, pointing to potential utility in cancer immunotherapy." (PMID 39502695, 2024).
infection (1 paper, 2022). The state of being infected such as from the introduction of a foreign agent such as serum, vaccine, antigenic substance or organism. "Flow cytometry results show that siRNA silencing the expression of SGK3, ULK3, ERBB4, STK17B can reduce the infection efficiency of ORFV-GFP virus, while siRNA silencing the expression of MST1R, PAK4, ERBB3 can increase the infection of ORFV-GFP virus efficient." (PMID 35401439, 2022).
STK17B also shares sentences with these, for which no sentence is quoted: colorectal cancer (3 papers); non-alcoholic fatty liver disease (3); type 1 diabetes (3); adenoma (2); colon cancer (2); cutaneous T-cell lymphoma (2); metabolic disease (2); adenocarcinoma (1); alcoholic fatty liver disease (1); Autoimmunity (1); colon squamous cell carcinoma (1); colorectal tumours (1); connective tissue disorder (1); experimental autoimmune encephalomyelitis (1); fibrosarcoma (1); glioma (1); heart disease (1); multiple myeloma (1); multiple sclerosis (1); myelodysplastic syndrome (1); nonalcoholic steatohepatitis (1); osteoarthritis (1); ovarian carcinoma (1); pancreatic cancer (1); Papillary Thyroid Cancer (1); thyroid tumor (1); triple-negative breast carcinoma (1); viral infection (1).